IL6 (interleukin 6)
Diseases named in the same sentence as IL6 in open-access papers (continued):
Sharing a sentence is not in itself a finding about the gene and the disease.
cancer (continued). "Also, a recent report has suggested that polymorphisms associated with low expression of anti-inflammatory IL-10 and TGF-β1 and immunomodulatory TNF-α, IFN-γ and IL-6 could be involved in the mechanisms of cancer progression and escape from immune surveillance." (PMID 18221542, 2008). "IL-6, IL-8, IL-12, IL-13, IFN-γ, MCP-1, MIP-1β and TNF-α were significantly more abundant in carcinoma than in normal breast." (PMID 17261184, 2007). "Circulating concentrations of IL-6, sgp130, sTNF-RII, IL-1Ra and IL-8 were all significantly elevated in cancer patients compared with controls (P<0.01)." (PMID 15570310, 2004). "C-reactive protein, interleukin-6, soluble gp130, soluble TNF receptor, interleukin-1 receptor antagonist and IL-8 concentrations were significantly elevated in cancer patients (P⩽0.001)." (PMID 15570310, 2004). "How VEGF-A is regulated in platelets or in megakaryocytes in cancer patients is unclear, but VEGF-A in epithelial cells is regulated by IL-6." (PMID 12454774, 2002). "In cancer, activated dendritic cells trigger naïve T cells through the T cell receptor to release TGF-β and IL-6, which activate Th17 to release IL-23 that binds IL-23R and, in an autocrine loop manner, stimulates effector or memory Th17 cells to secrete IL-17, IL-17F, and IL-22." (PMID 41596472, 2026). "Human lung fibroblasts, especially when activated into CAFs, secrete cytokines and growth factors (like TGF‐β, IL‐6, PDGF, EGF, HGF, CXCL‐12), ECM proteins, and remodeling enzymes like MMPs and pro‐invasive signals that potentiate cancer stemness and metastasis." (PMID 41537745, 2026). "Additionally, targeting key components of IL-6 signaling, such as IL-6Rs, gp130, STAT3, and JAK, with monoclonal antibodies, remains a major challenge in preclinical cancer research." (PMID 41596531, 2026). "Notably, D_FB1 displays elevated levels of other cancer‐ and inflammation‐related genes—such as DNAJB1, ZFP36, JUND, TNFAIP3 and IL6—further underscoring a microenvironment characterised by heightened cellular stress and chronic inflammation." (PMID 41055332, 2026). "IL-6 triggers inflammation and also regulates MAPK and JAK/STAT cancer-related pathways." (PMID 41596531, 2026). "We observed a significant inverse correlation between CTCF and IL6 gene expression levels in BrCa samples from patients with disease-free survival but not in those with cancer recurrence." (PMID 40143084, 2025). "IL-6 promotes EMT and is elevated in chronic inflammatory conditions and many cancers." (PMID 40868199, 2025). "Explicitly, IL‐6, IL‐8, and CCL2 facilitate the recruitment of M1‐type macrophages, T helper 1 cells, and NK cells to the TME, driving the immune clearance of senescent cancer cells." (PMID 39811803, 2025). "Additionally, cytokines such as IL-6, IL-1β, and TNF-α, play important roles in cancer initiation, growth, and metastasis development." (PMID 40699634, 2025). "This is the first study to prospectively evaluate the clinical value of novel biomarkers (IL-6, MPO, TNF-alpha) in cancer patients as potential biomarkers of cancer therapy-related cardiac dysfunction, defined according to current ESC cardio-oncology guidelines." (PMID 40362309, 2025). "Furthermore, in systemic infectious patients, monocytes/macrophages, NEPs, and cancer cells all produce YKL-40, and IL-6 plays a key role in mediating the regulation of plasma YKL-40 levels during inflammation." (PMID 39822987, 2025). "Meanwhile, chronic inflammation in adipose tissues increases the secretion of cytokines including IL-6 and TNF, which may contribute to cancer development." (PMID 40535346, 2025). "The ELISA analysis revealed that, without L-OHP, the IL-6 level in the co-culture supernatant was 2.4- and 2.9-fold higher than in supernatants from cancer cells or fibroblasts cultured alone, respectively." (PMID 40718440, 2025). "In other words, IL-6 has been shown to confer motility and invasiveness to non-invasive cancer cells." (PMID 40430040, 2025).
cancer (continued). "Similarly, the Piezo1–YAP axis in CAFs is activated under high mechanical tension, stimulating the secretion of collagen, fibronectin (FN), TGF-β, and interleukin-6 (IL-6), which in turn promotes ECM fibrosis and further enhances cancer cell invasion." (PMID 40821847, 2025). "The existing literature indicates that IL-6, NSP, pNF-H, and BDNF may serve as relevant biochemical markers of cognitive function in individuals with cancer." (PMID 41155494, 2025). "In addition, chromosomally unstable cancer cells increase the expression of IL6 and trigger IL6 signaling downstream through the cGAS-STING pathway, thereby promoting cancer cell survival and growth." (PMID 39744421, 2025). "To this end, we hypothesized that the binding of cytokines TGF-β1, IL-6, and HGF to their respective receptors induces cancer cells to adopt a mesenchymal metastatic phenotype through the Neu-1-MMP9-GPCR crosstalk signaling platform." (PMID 40227834, 2025). "Furthermore, in OC, IL6 accumulation stimulates the production of metalloproteinases, particularly MMP9, facilitating cancer cell invasion and the degradation of the extracellular basement membrane." (PMID 40427188, 2025). "The IL6/JAK2/STAT3 pathway is key to tumorigenesis, progression, metastasis, and immune escape, and the transcription factor STAT3 controls how quickly cells grow, move, and spread in a number of different types of cancer." (PMID 40874680, 2025). "Additionally, TEX can activate dendritic cells, leading to increased production of inflammatory mediators, including IL-6 and prostaglandin E1 (PGE1), which subsequently enhances cancer cell invasion and metastasis." (PMID 41502528, 2025). "A more reasonable strategy may be targeting both IL6 and MDM2 to decrease the pro-cancer consequences of IL6/GP130 signaling, both dependent and independent of MDM2 upregulation." (PMID 40961077, 2025). "However, the out-of-sample performance of IL-6 PRS has been previously assessed in the European Malmö Diet and Cancer study." (PMID 39800457, 2025). "In cancer cells, these exosomes have been found enriched with certain biomolecules such as NF-κB, STAT3, and pro-inflammatory cytokines (e.g., TNF-α, IL-1β, and IL-6); this means cancer cell-derived exosomes recruit immune cells to target sites." (PMID 40443670, 2025). "Our data therefore support cembranoids as intervention points to disrupt this loop, reducing IL-6 output without impairing essential Smad functions, and motivate further evaluation as anti-inflammatory, anti-cancer candidates." (PMID 41373438, 2025). "Notably, studies have shown that neutralizing IL6 or IL6R antibodies can reduce CAF-induced expression of HK2, emphasizing the important role of IL6 in promoting cancer cell growth." (PMID 40427188, 2025). "In addition, the advancement of monoclonal antibodies and receptor inhibitors aimed at pro-tumor cytokines like VEGF, IL-6, and TGF-β represents a significant achievement within cancer therapy." (PMID 41346580, 2025). "Existing literature suggests that IL-6, NSP, pNF-H, and BDNF may serve as important biochemical markers of cognitive function in individuals with cancer." (PMID 41155494, 2025). "In contrast, IL‐6, an inflammatory and immunosuppressive cytokine produced by both M1 and M2‐like macrophages, plays an important role in immune regulation, inflammation, and positively correlates with TNM stages of cancers." (PMID 41306557, 2025). "Additionally, IL‐6 activated the STAT3 tyrosine phosphorylation signaling pathway, promoted the M2 polarization of TAMs, and indirectly stimulated EMT in NSCLC cancer cells." (PMID 39927632, 2025). "Likewise, in the MDCa@RBC‐Alipo treatment group, significantly elevated levels of serum cytokines such as TNF‐α, IL‐6, and IL1‐β, which play crucial roles in cellular immunity against cancer, were observed." (PMID 40289661, 2025).
cancer (continued). "Moreover, activation of common pathways in some cancers, such as KRAS pathway, activation of IL6-JAK-STAT3/STAT5 pathway and activation of TNFα signaling pathway via NFkB were remarkably correlated." (PMID 39925804, 2025). "An inverse correlation between CTCF and IL6 expression levels was seen in disease-free survival BrCa patients but not in patients who experienced cancer recurrence." (PMID 40143084, 2025). "IL-6-driven STAT3 signaling may also promote LAG-3 expression, as shown in cancer patient-derived naïve CD8 T cells." (PMID 39981237, 2025). "Core nodes include IL6, MYC, VEGFA, EGFR, and ESR1, all of which play essential roles in cancer development and may act as critical molecular regulatory hubs." (PMID 40045358, 2025). "Significant controversies regarding the effects of senescence are particularly evident in the following cancer types: (a) Breast cancer: The SASP may promote cancer cell proliferation and invasion by secreting pro-inflammatory factors such as IL-6 and IL-8." (PMID 39836268, 2025). "The hypoxic obese PRAT microenvironment may promote cancer progression by hypoxia-induced factor 1α (HIF-1α) signaling activation and upregulation of CCL2, TNF-α, IL-10, IL-8, and IL-6 pro-inflammatory cytokine expression via NF-κB-pathway stimulation." (PMID 40227577, 2025). "Chronic inflammation, sustained by elevated levels of IL-6 and other pro-inflammatory cytokines, perpetuates persistent activation of STAT3, establishing a self-reinforcing cycle that drives the progression of cancer cachexia." (PMID 40704145, 2025). "Elevated levels of pro-inflammatory cytokines, such as IL-6 and TNF-α, which are commonly observed in cancer cachexia, trigger STAT3 activation, leading to the transcription of genes that exacerbate systemic inflammation, accelerate muscle protein degradation, and disrupt lipid metabolism." (PMID 40704145, 2025). "In cancers generally, and in UBC specifically, IL-6 is predominantly growth promoting." (PMID 40149682, 2025). "The reporter platform is a versatile tool, allowing to screen for and sort senescent cancer cells, allowing marker integration (for example incorporating IL6 upregulation as SASP marker) and enabling real‐time monitoring of senescence‐induction and ‐escape in cancer." (PMID 41159617, 2025). "Notably, the release of IL-6, TGF-β, and IGF-I by astrocytes promotes the proliferation of brain-tropic cancer cells in vitro." (PMID 41268299, 2025). "Additionally, chemotherapy patients showed increased inflammatory markers (e.g., IL-6, CRP) in CRC, which correlate with reduced survival and worse cancer health outcomes." (PMID 40862807, 2025). "Furthermore, complement signaling-mediated activation of NF-κB in CD10+GPR77+ CAFs drives cancer stem cell (CSC) enrichment and chemoresistance through IL-6 and IL-8 paracrine secretion." (PMID 40562870, 2025). "IL-6 and IL-8 have been shown to induce EMT in cancer cells in vitro." (PMID 41154660, 2025). "Since Fli-1 is a key regulator of various cytokines and chemokines, including IL-6, CCL2, CCL5, CXCL2, and CXCL13, the role of Fli-1 in promoting cancer development may partly be due to its role in driving the expression of these inflammatory mediators." (PMID 40305194, 2025). "PA induces anti-inflammatory effects on IL-6 that may reduce the activity of pro-inflammatory cytokines IL-1B and TNF-a, positively affecting cancer-related fatigue." (PMID 39915872, 2025). "In addition, we analyzed the protein levels of IL6 and markers of TAMs, including matrix metalloproteinase 9 (MMP9) and arginase 1 (Arg1), in HCC cancer tissues and adjacent tissues." (PMID 39744421, 2025). "According to the results of GSEA in pan-cancer, NCBP2 was closely related to immune related pathways, such as IFN-alpha response, IFN-gamma response, IL-6/JAK/STAT3 signaling, IL-2/STAT5 signaling, allograft-rejection pathways, inflammatory response, and TNF alpha signaling-via NFKB." (PMID 40124611, 2025).
cancer (continued). "We further analyzed the control post-intervention studies in the cancer group: the AC (SMD = 0.07; 95% CI, −0.30 to 0.44) exerted a mild increasing effect, and the TAU (SMD = −0.64; 95% CI, −3.08 to 1.80) exerted an obvious decreasing effect on IL-6." (PMID 40281902, 2025). "Cytokines like IL-10 and IL-6 are key to regulating immune responses within the pre-metastatic niche (PMN), and they contribute to forming the immunosuppressive environment typical of cancer progression." (PMID 41583453, 2025). "Moreover, various pro‐inflammatory markers i.e., IL‐1, IL‐6, TNF‐α, IFN‐γ, TGF‐β and growth factors (VEGF, EGF, IGF‐2) are also involved in cancer progression." (PMID 40755497, 2025). "Interleukin-6 (IL-6) family cytokines activate the JAK/STAT3 pathway via the IL-6Rα/gp130 receptor complex, thereby inducing acute-phase protein synthesis, skeletal muscle proteolysis, and browning of adipose tissue—core phenotypic features of cancer cachexia." (PMID 41002589, 2025). "It has been reported that serum levels of IL-6, CRP, and other markers are significantly increased in patients with metastatic colorectal cancer, and their combined detection is conducive to predicting cancer mortality after surgery." (PMID 40919145, 2025). "Additionally, M2 macrophage and MDSCs secrete cytokines like IL-6 and IL-11, which activate STAT3 and create a signalling loop that fosters a TME favourable for cancer cells." (PMID 40407951, 2025). "Additionally, MCPIP1 inhibits cancer stemness and mixed EMT of PC cells by suppressing the IL6/JAK2/STAT3 axis." (PMID 40874680, 2025). "At the same time, an abundance of inflammatory cytokines and cytokine receptors in the common target may be engaged in the cancer pathway, including TNF, IL6, and IL2." (PMID 39492771, 2025). "Furthermore, SASP components, such as IL-6, have been shown to activate the STAT3 signaling pathway, which supports cancer cell proliferation and resistance to apoptosis." (PMID 40277546, 2025). "In addition, previous studies have indicated that IL‐8, IL‐6 and TNF‐α are cytotoxic mediators of the link between inflammation and cancer." (PMID 40289540, 2025). "One possible explanation is that TIC10‐induced TRAIL activates the noncanonical NFκB2 pathway in cancer cells, leading to the production of cytokines such as IL‐6, IL‐10, and GM‐CSF." (PMID 40673385, 2025). "γδ T cells can also produce IL-6, which may significantly influence the TME and impact the immune response to cancer." (PMID 40801630, 2025). "However, treatment with ECH147 resulted in a sustained decrease of IL-6 levels in both normal and cancerous cells, with a notably stronger reduction observed in the SW1116 cancer cell line." (PMID 41256010, 2025). "Furthermore, IL-1α, IL-6, and IL-8 mediate the recruitment of M1-like macrophages, helper T cells, and NK cells into the TME, further driving the clearance of cancer cells." (PMID 40149983, 2025). "Besides, irisin reversed IL-6-induced EMT process in OS cells via the STAT3/Snail signaling pathway, consequently suppressing cancer cell migration and invasion." (PMID 40909292, 2025). "Our previous study also confirmed that the NF-κB/IL-6/STAT3 positive feedback loop plays a crucial role in inflammation and pro-survival and might be an essential link between inflammation and cancer." (PMID 40129988, 2025). "Additionally, cancer‐related inflammation, characterized by elevated cytokines such as TNF‐α and IL‐6, further disrupts insulin signaling, exacerbating metabolic dysfunction." (PMID 40195579, 2025).
cancer (continued). "In vitro studies demonstrated that these compounds induce a significant increase of TNF-α, IL-12, IL-6 and IL-1β mRNA expression and downregulate M2-like genes like IL-10, Ym-1, CD206 and Arg-1 in several models of cancer (e.g., breast cancer, colon cancer, MM)." (PMID 38397187, 2024). "Furthermore, increasing evidence indicates that the enhanced catabolism experienced by cachectic cancer patients is mediated primarily by increases in pro-inflammatory cytokines, including TNF-α, IL-1, and IL-6." (PMID 38339292, 2024). "Obviously, IL6 elevation in both cancer and COVID-19 does not necessarily mean that there is a link between them." (PMID 39770330, 2024). "Enhanced levels of intracellular cytokines, such as interleukin 2(IL2), TNF-α, interferon-gamma (IFN-γ), and IL6, were observed within the memory subpopulation, indicating that IL7 may stimulate a memory immune response targeting cancer." (PMID 38289597, 2024). "In addition, leptin and adipocyte-derived IL-6 enhance the expression of lysyl hydroxylase (PLOD2) by activating the JAK/STAT3 and PI3K/AKT signaling pathways, ultimately facilitating cancer cell metastasis." (PMID 39192979, 2024). "Hypoxia and increased synthesis of vascular endothelial growth factor (VEGF), macrophage colony-stimulating factor (M-CSF), IL-6, IDO, extracellular adenosine, and immunosuppressive cytokines, including IL-10 and TGF-β, characterize the cancer site's immunosuppressive milieu." (PMID 38962577, 2024). "In the 2D coculture system, IL-6 and IL-8 overexpression was not enough to increase drug resistance in cancer cells, suggesting that either another factor or the physical interaction between the cell types is missing." (PMID 38674102, 2024). "Ultimately, treating HepG2 cancer cells with Pitavastatin affected significant activation of caspase-3 accompanied by down-regulation of cellular apoptotic biomarkers such as IDO, TDO, STAT3, P21, P27, IL-6, and AhR." (PMID 38653790, 2024). "Overall, these studies highlight the critical roles of IL6 and IL6R, as well as CD46 and JAG1, in the survival and invasive capacity of cancer cells, and their broad promise as targets for antitumor therapies, as well as exploring the possibility of combining them with other therapeutic agents." (PMID 38571938, 2024). "In specific cancer contexts, such as LIHC, KLHL23 expression exhibited a negative association with the IL6-JAK-STAT3 signaling pathway, but a positive association with the G2M checkpoint and MYC gene targeting signaling pathway." (PMID 39636292, 2024). "Recent studies have highlighted the potential of CNTO328, a chimeric murine anti-human IL6 antibody, to neutralize the function of IL6 and reduce the incidence of cancer-related anorexia and cachexia without serious adverse effects." (PMID 39766086, 2024). "Clinical trials of agents targeting TNF‐α in patients with cancer cachexia are not conclusive, while those targeting both IL‐6 and TNF‐α show greater promise." (PMID 38481033, 2024). "Increased levels of IL-6 and C-reactive protein (CRP) alongside MMP9 with advancing CRC stages indicate the role of systemic inflammation in modulating the tumor microenvironment and driving cancer progression." (PMID 39664453, 2024). "Either way, these results do not diminish the importance of IL-6 during cancer progression and metastasis." (PMID 38396821, 2024). "In cancer, IL-6 inhibitors have been described to counteract various pro-tumorigenic activities, but clinical cancer control in humans has not been reported." (PMID 39518029, 2024). "In various cancers, different additional EMT-promoting effects of IL-6 have been described." (PMID 39201656, 2024). "SLC40A1+ TAMs exhibited high expression level of the ferroportin gene SLC40A1, which promotes the production of pro-inflammatory cytokines such as IL-6 and IL-23 while inhibiting the production of the key inflammatory regulator IL-1β in the TME, leading to the poor prognosis for cancer." (PMID 39232806, 2024).